MMP2 (matrix metallopeptidase 2)
Diseases named in the same sentence as MMP2 in open-access papers (continued):
Sharing a sentence is not in itself a finding about the gene and the disease.
seminoma (6 papers, 2019 to 2023). A radiosensitive malignant germ cell tumor found in the testis (especially undescended), and extragonadal sites (anterior mediastinum and pineal gland). "First, we showed that the invasive behavior of seminoma cells depends on the PTTG1-mediated transcriptional activation of the MMP-2 gene." (PMID 38069214, 2023). "We previously demonstrated that nuclear PTTG1 promotes seminoma tumor invasion through its transcriptional activity on matrix metalloproteinase 2 (MMP-2) and E-cadherin (CDH1)." (PMID 38069214, 2023). "We previously showed the role of nuclear PTTG1 in promoting invasiveness, through its transcriptional target MMP2, in seminoma in vitro models." (PMID 36230799, 2022). "Exposure of the human gonocyte-like seminoma cell line, TCam-2, to activin A increased both MMP2 transcript and protein levels." (PMID 35721752, 2022). "This phenomenon has been correlated with increased MMP-2 expression and with more invasive properties of seminoma cell lines." (PMID 36230799, 2022). "A previous study reported that PTTG1, an overexpressed gene in seminoma tumor, promoted the migration and invasion of tumor cells via activation of MMP-2." (PMID 35251171, 2022). "We previously reported that PTTG1 expression, specifically its nuclear localization in seminoma cell lines is responsible for a more aggressive phenotype via its migratory properties, Matrigel invasion capability and MMP-2 proteolytic activity." (PMID 36230799, 2022). "Lastly, we have recently demonstrated the role of PTTG1 nuclear localization in promoting invasiveness and metastatic process in different seminoma cell lines via the increase of MMP2 levels." (PMID 36230799, 2022). "Previously, we found that PTTG1 nuclear localization was strongly correlated with MMP-2 activity in our seminoma in vitro model." (PMID 33430117, 2021). "Since it has been reported that PTTG1 enhances MMP-2 expression and activity, we investigated metalloproteinases secretion/activity in the seminoma cell lines by zymography." (PMID 33430117, 2021). "The analysis demonstrates a significantly higher level of MMP-2 in seminomas compared to non-seminoma tumors, supporting the role of PTTG1 nuclear activity in driving MMP-2 levels and hence in promoting invasiveness of seminoma tumors." (PMID 33430117, 2021). "The Atlas database analysis confirmed the prevalent nuclear localization of PTTG1 in seminoma tumors, and the strong correlation between its nuclear localization and the increased expression of MMP2 versus nonseminoma tumors." (PMID 36230799, 2022). "Analysis of Atlas in vivo data strongly supported these results, revealing an exclusive PTTG1 nuclear localization and a concomitant increase of MMP-2 levels in seminoma compared to non-seminoma tumors." (PMID 33430117, 2021). "Analysis of human testicular tumors from the Atlas database revealed an exclusive PTTG1 nuclear localization and a concomitant increase of MMP-2 levels in seminoma compared to non-seminoma tumors." (PMID 33430117, 2021). "Atlas database analysis revealed that PTTG1 was localized in the nucleus in seminoma compared with non-seminoma tumors, and that MMP-2 levels were significantly higher in seminomas." (PMID 33430117, 2021). "In order to validate in vivo the role of PTTG1 in seminoma, we wondered whether PTTG1, PBF, and MMP-2 showed specific behavior in human testicular tumors." (PMID 33430117, 2021). "An interrogation of the same Atlas database, to evaluate MMP-2 levels in seminoma compared with non-seminoma tumors, showed a significant higher level of MMP-2 in seminoma samples, supporting the role of PTTG1 nuclear transcriptional activity in driving MMP-2 levels." (PMID 33430117, 2021). "Importantly, this analysis further demonstrated a significant higher level of MMP-2 in seminomas compared to non-seminoma tumors, supporting the role of PTTG1 nuclear activity in driving MMP-2 levels and hence in promoting invasiveness of these tumors." (PMID 33430117, 2021).
seminoma (continued). "Further investigation are needed to extend the number of clinical cases investigated, to analyze the co-localization of PTTG1 with MMP2, MMP9, VEGF and to clarify if a functional abrogation of PTTG1 might represent a novel therapeutic approaches in the clinical management of seminoma." (PMID 31572301, 2019). "The Atlas database interrogation revealed that in seminomas, there was an increased nuclear PTTG1 localization along with higher levels of MMP-2 compared to nonseminoma tumors." (PMID 36230799, 2022).
steatosis (6 papers, 2020 to 2025). Increased lipid within the cytoplasm of cells. "However, another report showed higher MMP2 liver expression, serum concentration of MMP2 and hyaluronic acid in patients with NASH compared to those with simple steatosis even when excluding patients with severe fibrosis." (PMID 37445827, 2023). "Here we showed that, despite lower steatosis in MCD-fed MyMRKO mice, the histological and molecular features of fibrosis remain unaffected by MR deletion in myeloid cells (including higher levels of profibrotic markers Col1A, Mmp-2, Timp-1, and Tgfβ)." (PMID 33391254, 2020). "Indeed, serum concentrations of MMP2, MMP9, TIMP1, TIMP2, MMP7, TGF-β1 and -β2 were found to be significantly higher in NAFLD patients compared to controls, yet these markers are unable to distinguish between steatosis and steatohepatitis." (PMID 37445827, 2023). "However, they concluded that MMP-2 is not a marker that would allow differentiation between simple steatosis and NASH." (PMID 36769216, 2023). "Although ETs do not regulate cell steatosis but cause inflammation in HepaRG and HCC cells, here, we further investigated the effect of ETs (single exposure and in combination) on the expression of cell fibrosis markers such as AST, FGF-23, Cyt-7, p21, TGF-β, TIMP2, and MMP2." (PMID 39771071, 2024).
systemic lupus erythematosus (6 papers, 2004 to 2025). An autoimmune multi-organ disease typically associated with vasculopathy and autoantibody production. "MMP-2, TIMP-2, and MMP-2/TIMP-2 ratios may act as biomarkers for susceptibility to systemic lupus erythematosus (SLE)." (PMID 33777140, 2021). "In one study looking at patients with systemic lupus erythematosus (SLE), MMP-2 inhibition resulted in lower levels of NETs and improved endothelial function." (PMID 36012562, 2022). "In addition, several autoimmunity-related proteins are linked to coagulation (e.g., AGT, F2) and to specific ADs, such as systemic lupus erythematosus (e.g., AGT, C1S, C7, MMP2, VWF) or autoimmune rheumatic diseases (e.g., ADIPOQ, AGT, MASP1, MMP2)." (PMID 40546301, 2025). "Our results suggest that MMP-9 but not MMP-2 actively participates in brain destruction in CNS lupus." (PMID 15535833, 2004).
tongue squamous cell carcinoma (6 papers, 2014 to 2024). A squamous cell carcinoma that arises from the tongue. "It inhibited nuclear translocation of the transcription factor AP-1 to the MMP-2 promoter, decreased MMP-2 production, and prevented migration and invasion in human tongue squamous cell carcinoma cells (SCC4 cells)." (PMID 38672151, 2024). "An in vitro study showed the inhibitory effects of grape seed PA on the secretion of MMP-2 and MMP-9 in the tongue squamous cell carcinoma cell line Tca8113, indicating the anti-metastatic capability of PA." (PMID 36330492, 2022). "Silencing uPAR can inhibit the expression of the MMP2, MMP9 and P-ERK proteins in oral and tongue squamous cell carcinoma and attenuate cell proliferation." (PMID 34729105, 2021). "In human tongue squamous cell carcinoma cells (SCC4 cells), Kae inhibited migration and invasion, reduced the protein expression of MMP-2, and decreased the nuclear translocation of the transcription factor AP-1 to the MMP-2 promoter." (PMID 33498927, 2021).
venous ulcers (6 papers, 2021 to 2025). "Some of the features of advanced stages of CVD, i.e., lipodermatosclerosis and/or venous ulcer, may be linked with increased MMP activity and ECM turnover associated with increased mRNA expression and MMP-1 and MMP-2 protein levels." (PMID 35807509, 2022). "Recently, it was demonstrated that the degree of expression of MMP-1 and MMP-2 evaluated in venous ulcer biopsies, as well as the decrease in their expression along the observation period (4 weeks) represented a predictor of a more successful healing of the venous ulcers evaluated." (PMID 34681353, 2021). "Nanocrystalline silver dressings significantly reduce persistent venous ulcers and inflammatory markers MMP‐9 and MMP‐2 in a patient with chronic wounds, highlighting silver's anti‐inflammatory effects." (PMID 39707715, 2025). "In fact, studies show that MMP-2 and MMP-9 levels are particularly high in the tissues of subjects with venous ulcers in the active phase, and that levels are reduced significantly with the healing of the ulcer." (PMID 40362286, 2025). "Lipodermatosclerosis (preceding phase of venous ulcer) is characterized by an increase in mRNA and protein expression for MMP-1 and MMP-2." (PMID 37175078, 2023). "Elevated MMP-2 and MMP-9 levels are commonly found in tissues affected by venous ulcers." (PMID 40362286, 2025). "In venous ulcers fluids, MMP-1 and MMP-2 are strongly active." (PMID 37175078, 2023).
acute respiratory distress syndrome (5 papers, 2021 to 2025). Progressive and life-threatening pulmonary distress in the absence of an underlying pulmonary condition, usually following major trauma or surgery. "The secreted MMP-2 thus may cause the death or distress of lung epithelial cells causing the acute respiratory distress syndrome." (PMID 41459161, 2025). "As we have speculated that MMPs (especially MMP-2) may be responsible for causing the epithelial distress or epithelial apoptosis and may be responsible for the development of severe form of acute respiratory distress syndrome." (PMID 41459161, 2025). "MMP-2 and MMP-9 have been found to play an important role in ALI, acute respiratory distress syndrome (ARDS), and pulmonary fibrosis." (PMID 35872761, 2022).
age-related macular degeneration (5 papers, 2013 to 2023). Age-related loss of vision in the central portion of the retina (macula), secondary to retinal degeneration. "Summary of meta-analysis results for the association of rs243865 MMP-2 polymorphism with age-related macular degeneration by age." (PMID 30845235, 2019). "Genotype and allelic distribution of rs243865 MMP-2 polymorphism in age-related macular degeneration patients and healthy subjects." (PMID 30845235, 2019). "Several researchers have suggested that the rs243865 (16q13-q21) polymorphism in the promoter region of the metalloproteinase-2 (MMP-2) gene could be associated with an increased risk of developing age-related macular degeneration (AMD)." (PMID 30845235, 2019). "The types and expression levels of MMPs vary by the disease; for example, in age-related macular degeneration, the expression of MMP-2 and MMP-9 is significantly reduced." (PMID 36973823, 2023). "In eyes at high risk of age-related macular degeneration, one study identified lower ADAMTS9 mRNA levels, which could lead to higher MT1-MMP activity, and thus greater pro-MMP2 activation, together promoting retinal angiogenesis." (PMID 37169079, 2023).
allergic asthma (5 papers, 2013 to 2023). A asthma with a basis in a pathological type I hypersensitivity reaction. "Inhibition of MMP2 significantly stimulated elastin expression in airway fibroblasts from patients with allergic asthma when compared to those from normal controls." (PMID 32719611, 2020). "Overall, these results suggest that stimulation of M1 differentiation by MMP-2 is one possible explanation for the protective activity of human MMP-2 overexpression in allergic asthma." (PMID 31428095, 2019). "These prior observations led us to hypothesize that MMP-2 protects against allergic asthma because it downregulates Th2 immune response by promoting the differentiation of macrophages to M1 phenotype." (PMID 31428095, 2019). "In this context and considering the low plasma level of MMP-2 in our asthmatic patients compared to controls, it may be permissible to speculate that low MMP-2 is associated with susceptibility to allergic asthma." (PMID 31428095, 2019). "We note that airways infection with respiratory syncytial virus (RSV), the most common viral respiratory pathogen in small children which is widely considered as a risk factor for the development of allergic asthma later in life is characterized by an increased expression of SNAI1, MMP-2, and TGFβ1." (PMID 24228254, 2013). "Similar to these results, the extract of Lonicera japonica decreased activities of MMP-2 and MMP-9 against ovalbumin-induced allergic asthma." (PMID 37107342, 2023).
anaplastic astrocytoma (5 papers, 2008 to 2025). "Findings indicate that MMP-2 expression is significantly elevated in GBM than in normal brain tissue, diffuse astrocytoma, and anaplastic astrocytoma." (PMID 40512281, 2025). "MMP-2 expression was found to be significantly higher in GBM compared to normal brain tissue (p < 0.001), diffuse astrocytoma (p < 0.001), and anaplastic astrocytoma (p < 0.05)." (PMID 33227903, 2020).
autoimmune disease (5 papers, 2011 to 2023). A disorder resulting from loss of function or tissue destruction of an organ or multiple organs, arising from humoral or cellular immune responses of the individual to their own tissue constituents. "In patients with various underlying medical conditions, ranging from autoimmune disease to cardiac disease, use of statins resulted in decreased IL6, IL10, IP10, MMP2 and MMP610–12." (PMID 30464247, 2018).
B cell lymphoma (5 papers, 2013 to 2025). "Other studies have also identified MMP-2 rs243865 as a potential molecular risk factor for B-cell non-Hodgkin’s lymphoma and T-cell acute lymphoblastic leukemia." (PMID 40724896, 2025). "IL-2R on T cells and B cell lymphoma cells are composed of α, β, and γ chains, and sIL-2R is a soluble form of the α chain of IL-2R, which is cleaved by matrix metalloproteinases (MMP)-2 and MMP-9." (PMID 36357882, 2022). "Further analyses revealed that alteration of the expression of signature genes by ColXV was associated with B-cell lymphoma family and ECM remodeling, especially Bcl-2, Col1a1, Col6a1, MMP-2 and MMP-9." (PMID 32024006, 2020). "MMP-2 expression was grade 2 in all T-cell lymphomas; grade 1 in 19 HG B-cell lymphomas and grade 0 in the remaining 7 B-cell lymphomas (3 HG and 4 LG)." (PMID 23641796, 2013). "The elevated levels of vitreous sIL-2R may be the result of the cleavage of IL-2R on the surface of T cells and B cell lymphoma cells with activated MMP-2 and MMP-9." (PMID 36357882, 2022). "We also performed gelatine zymography in T-cell and B-cell lymphomas to investigate the activity of MMP-2 and MMP-9, but no catalytic activity was detected." (PMID 23641796, 2013).
bone tumor (5 papers, 2010 to 2025). "CD147 expression levels were markedly up-regulated over half of the expression levels in the benign bone tumor tissues as well as the MMP-2 and MMP-9 expression levels." (PMID 30043854, 2018). "This study underscores the potential carcinogenic effects of ATBC in bone cancer, identifying key targets such as STAT3, EGFR, MMP9, MAPK1, and MMP2." (PMID 40625361, 2025). "We identified 73 overlapping genes between ATBC exposure and bone cancer, subsequently prioritizing STAT3, EGFR, MMP9, MAPK1, and MMP2 as core targets." (PMID 40625361, 2025). "Notably, among these core targets, STAT3, EGFR, MMP9, MAPK1, and MMP2 were identified as the top five targets based on MCC values, serving as the hub targets of ATBC-induced bone cancer." (PMID 40625361, 2025). "Among them, the insulin growth factor, the fibroblast growth factor, the interleukin Il-6, the chemokine CCL5 (RANTES) and the matrix metalloproteinases MMP-2 and MT1-MMP are few of the mediators that could have a particular role in bone tumor development." (PMID 20544017, 2010).
brain injury (5 papers, 2015 to 2023). Acute and chronic (see also brain INJURIES, CHRONIC) injuries to the brain, including the cerebral hemispheres, CEREBELLUM, and brain STEM. "An involvement of MMP2 in various regenerative processes after brain injuries has been reported (Verslegers, Lemmens, van Hove, & Moons, 2013)." (PMID 31271523, 2019). "A dual inhibitor of MMP-2 and MMP-9, known as SB-3CT, reduced brain lesion volumes and prevented neuronal loss and dendritic degeneration in an experimental mouse model of traumatic brain injury." (PMID 37109410, 2023). "Thus, our data support a protective PARP-dependent role of MMP-2 activity in hepatic IRI and are in line with the results of a recent study, which showed that PJ34 reduces MMP-9 and protects against traumatic brain injury." (PMID 26355684, 2015).
cognitive decline (5 papers, 2016 to 2025). "Notably, the progressive and sustained vasoconstriction demonstrated strongest correlation with cognitive decline compared to the plateaued/decreased developmental patterns and weaker correlations observed with MMP2 and fibrinogen." (PMID 41268782, 2025). "In addition, this reduction in MMP-2/9 correlated with the observed cognitive decline in all groups of mice, reported in the T-water maze paradigm (Spearman r = −0.4254, *p = 0.0121) and the NOR paradigm (Spearman r = 0.3510, *p = 0.0418)." (PMID 27661129, 2016).
colon adenocarcinoma (5 papers, 2013 to 2025). "In vitro MMP-2 and 9 inhibitions were determined on colon adenocarcinoma (HT29) cells, as well as by measuring the expression levels of genes related to these enzymes." (PMID 34948082, 2021).
dengue (5 papers, 2014 to 2025). "In the present study we found that, MMP-2 is secreted by the neutrophils when they are activated by dengue NS1 antigen and it may cause sever dengue pathogenesis." (PMID 41459161, 2025). "This confirms that neutrophils mediated MMP-2 causes the lung epithelial cells death/distress and may be one of the important mechanisms of dengue pathogenesis associated to lung dysfunctions or ARDS." (PMID 41459161, 2025). "This proofs that neutrophils mediated MMP2 release caused the ARDS in sever dengue pathogenesis." (PMID 41459161, 2025). "In our previous study we have shown that, mRNA expression profile of matrix metalloproteases, including MMP2 are highly upregulated in neutrophils in response to dengue NS1 antigen." (PMID 41459161, 2025). "Our findings further highlight the MMP-2 as an important potential target for the development of dengue therapeutics." (PMID 41459161, 2025). "To further proof the MMP-2 mediated mechanism of lung dysfunctions or ARDS in dengue pathogenesis we have tested this hypothesis in Balb/c mice using NS1 antigen alone and in combination with atorvastatin." (PMID 41459161, 2025). "Notably, MMP‐2 and MMP‐9 levels are significantly elevated in severe dengue and have been associated with impaired immune responses and increased disease complications in affected patients." (PMID 40910405, 2025). "We found that, MMP-2 concentrations have significantly upregulated the expression profile of apoptotic genes, that is, caspase-3, Bad, Bax, caspase-6, and DAPK-1 in lung epithelial cells suggesting its apoptosis causing property in dengue pathogenesis." (PMID 41459161, 2025). "This study suggests the role of MMP9 and MMP2 in dengue pathogenesis." (PMID 24727912, 2014). "In particular, interleukin‐10, interferon‐gamma and matrix metalloproteinases (MMP‐2 and MMP‐9), all of which are elevated in severe dengue, have been shown to enhance the production of sHLA‐G." (PMID 40910405, 2025).